ATF6 (activating transcription factor 6)
Diseases named in the same sentence as ATF6 in open-access papers (continued):
Sharing a sentence is not in itself a finding about the gene and the disease.
infection (continued). "In addition, they detected the translocation of XBP1 and ATF6 to the nucleus of infected cells in the brain of mice five days after infection, indicating activation of these pathways." (PMID 39459886, 2024). "Moreover, the implication of the ATF6 pathway was demonstrated in the induction of autophagy following infection with the Peste des Petits Ruminants Virus, a member of the Morbillivirus genus." (PMID 39772156, 2024). "The ATF6α activation upon infection has been observed for other large DNA viruses as well." (PMID 37434252, 2023). "In this study, we found that H37Ra infection induced Herp production in an ATF6-dependent manner." (PMID 37800958, 2023). "On the other hand, the data presented here suggest that targeting ATF6α may be beneficial in selective contexts of inflammation that evoke an IL-12/IL-6 cytokine response, which may include infection with intracellular bacteria or certain autoimmune contexts." (PMID 37025177, 2023). "For example, the expression of PERK and ATF‐6 in Ad‐Vp3‐infected cells were significantly higher at 12 and 24 h than in cells infected with Ad‐Mock but were significantly lower at 48 and 72 h post‐infection (p < 0.01)." (PMID 36515089, 2023). "The ATF6 pathway of ER stress was seemingly unaffected by infection." (PMID 36705566, 2023). "However, when infections were carried out with functional viruses but in the presence of a viral DNA replication inhibitor (Ara,C), residual ATF6α transcriptional activity was detected." (PMID 37434252, 2023). "In addition, we obtained flies with fat body-specific RNAi of Sip3 combined with Xbp1, PERK, or Atf6 RNAi and conducted infection experiments." (PMID 36741393, 2022). "ATF6 is recruited to the LCV during infection and might serve to sense changes within the LCV environment." (PMID 34635501, 2021). "In addition, ATF6 levels (full length and cleaved) significantly decrease at later time points of infection." (PMID 33996638, 2021). "Therefore, the consequences of infection can be due to P-eIF2α from PERK activation or dependent on the two other branches of the UPR (ATF6 and IRE1)." (PMID 33996904, 2021). "An attractive model to test in future studies would be to examine whether L.p. uses ATF6 for lipid synthesis to actively contribute to the growing membrane of the LCV during the course of the infection." (PMID 34635501, 2021). "A late induction of the ATF6 pathway could be observed for TBEV Neudoerfl infected astrocytoma SNB19 cells at 72 h post infection." (PMID 34834970, 2021). "Interestingly, we discover novel L.p. effectors that play a role in the activation of ATF6 during infection." (PMID 34635501, 2021). "As L.p. infection causes an inhibition of protein synthesis, we considered this deregulation might contribute to the processing of ATF6 during infection." (PMID 34635501, 2021). "To gain more insight into ATF6 mediated transcript induction patterns during L.p. infection, we examined the gene activation profile of BiP at different time points over the course of an infection." (PMID 34635501, 2021). "TMUV infection slightly increased the level of ATF6 at 12 h and 24 h post-infection." (PMID 30670030, 2019). "ATF6-dependent genes, such as Xbp1 and BiP, also increased following infection." (PMID 31467282, 2019). "PERK and ATF6 signaling pathways play critical roles in SFTSV infection processes." (PMID 30842332, 2019). "WNVKUN infection can activate the ATF6 pathway to facilitate replication and immune evasion." (PMID 30842332, 2019). "Moreover, the level of cleaved ATF6 in infected cells increased with the extension of infection time." (PMID 30717233, 2019). "The Uganda strain (MR766) caused upregulation of the protein kinase R (PKR)-like endoplasmic reticulum kinase (PERK), inositol requiring enzyme 1α (IRE-1α) and activating transcription factor-6 α (ATF6α) proteins, while infection with the Honduran strain induced expression of IRE-1α and ATF6α." (PMID 30735502, 2019).
infection (continued). "Thus, we examined the cleavage of ATF6 by Western blotting at 3 h, 6 h and 9 h post-infection (MOI = 5)." (PMID 30717233, 2019). "Nevertheless, further investigation is needed to determine whether temporary activation of ATF6 affects TMUV replication during infection." (PMID 30670030, 2019). "Maybe, CSFV also activates UPR in a temporal manner, and the ATF-6 UPR pathway is probably suppressed to normal level by viral proteins at middle-late stage of CSFV infection for maintaining persist infection, which need further investigations." (PMID 31798542, 2019). "The promoting effect of ATF6 is clearly inhibited after siRunx2 infection." (PMID 26374329, 2015). "In MHV-infected cells, significant cleavage of ATF6 could be detected starting from 7 h post-infection." (PMID 24987391, 2014). "However, the levels of both full length and cleaved ATF6 protein diminished at later time points during infection." (PMID 24987391, 2014). "However, it remains unknown which aspects of ATF6 activation during infection are host-driven or effector-driven." (PMID 34635501, 2021). "Other authors reported that the virus disarms the UPR in the early phase of the infection, activating only the ATF6 pathway and leaving the GRP78 levels unchanged and IRE1 inactive, to prevent further activation of ERAD that may be detrimental to virus replication." (PMID 32610629, 2020). "Our present investigation revealed that infection with TGEV remarkably increased the protein levels of GRP78, ATF6, CHOP, as well as PERK phosphorylation level in jejunal mucosa." (PMID 41138168, 2025). "In this study, we observed that PTV-GXLZ2024 infection specifically activated the PERK-eIF2α-ATF4 pathway, while the ATF6 and IRE1 pathways remained unaffected." (PMID 41012628, 2025). "In contrast, ATF6 expression was downregulated, suggesting a possible suppression or shutdown of this UPR branch in response to infection." (PMID 41157573, 2025). "Infection with TGEV remarkably elevated the levels of GRP78, ATF6, CHOP protein, and PERK phosphorylation level in jejunal mucosa (P < 0.05)." (PMID 41138168, 2025). "Transduction of the XC45-6S ATF6α/IRE1 dual UPR reporter cells was performed at a coverage of ~640×, with a multiplicity of infection (MOI) of 0.3, intentionally set low to disfavour acquisition of more than one sgRNA by any one cell." (PMID 39073063, 2024). "Collectively, our results indicate that VACV induces and exploits ATF6α signaling and the UPR upon infection in order to maximize its replicative success." (PMID 37434252, 2023). "Further analysis of the ATF6 and PERK pathways in DBT-WT cells revealed that p90ATF6 protein levels were significantly upregulated 6 h as well as 9 h post MHV-A59 infection." (PMID 36572185, 2023). "HCMV modulates all the three branches of UPR signaling viz., PKR-like ER kinase (PERK), activating transcription factor-6 (ATF-6), and inositol requiring enzyme- 1(IRE1) during its infection." (PMID 36156601, 2022). "ATF6 was potentially regulated by miR-133a-5p (upregulated at 50 DPI) and miR-4331 (downregulated at 10 DPI), showing the significant difference in the ATF6-induced UPR to ER stress in T. gondii-infected brain during the acute and chronic phases of infection." (PMID 35360170, 2022). "For example, Mycobacterium avium, increases activation of IRE1, ATF6, and PERK following infection of host cells." (PMID 33996904, 2021). "Taking this into account, transcriptomic analysis resulted in an increase in XBP1, IRE1α, CHOP, ATF6, ATF4, PERK, EIF2α and BIP expression after infection with NOX5-β adenovirus at all time conditions." (PMID 33572841, 2021). "Both the Atf6−/− and PERK−/− cell lines exhibited the same pattern of ERK1/2 phosphorylation and Egr1 accumulation upon T3SS1+ infection as wild-type MEFs, indicating that VopQ’s activation of ERK1/2 was specifically IRE1 dependent." (PMID 33563785, 2021).
infection (continued). "Reports in human fibrosarcoma cells showed UPR activation in a time-dependent manner; with PERK induced at early stages of infection, followed by the IRE1α-XBP1 axis and, finally, ATF6 in mid and late replication cycle stages." (PMID 32106582, 2020). "The results showed an increased level of the 50-kDa ATF6 fragment in HRV16-infected cells, indicating that HRV16 infection activated the ATF6 pathway." (PMID 30717233, 2019). "Our results showed that both HRV16 infection and 2B gene transfection increased the expression of ER chaperone GRP78, and induced phosphorylation of PERK and cleavage of ATF6 in a time-dependent manner." (PMID 30717233, 2019). "ΔGntR infection increased the expression of ER stress marker genes GRP78, ATF6, and PERK in the early stages of its intracellular cycle but decreased the expression of these genes in the late stages." (PMID 29435171, 2018). "For instance, the induction of Xbp-1 splicing after infection with JEV, TBEV, and USUV, the expression of CHOP during JEV infection, and the cleavage of ATF6 in TBEV-infected cells have been described." (PMID 24917859, 2014). "At 33 hr post-infection, several major components of the UPR pathway were up-regulated, including BiP, PERK, ATF6, IRE1, GADD34, CHOP and XBP-1." (PMID 23170826, 2012). "The subcellular localization of ATF6 and thus activation of the UPR was determined in OSU and RRV infected MA104 cells seven hours post-infection." (PMID 21774819, 2011). "Remarkably, similar outcomes were observed following infection with PRRSV where the proteolytic cleavage of ATF6 does not occur, nor is there an increase in the expression of ATF6 target genes, such calnexin or calreticulin." (PMID 41157573, 2025). "We reveal that, with the exception of atf6, which displayed comparatively delayed activation, transcript levels of all UPR genes we measured harmoniously activate, peak, then diminish prior to the advent of appreciable infection-induced mortality." (PMID 41218768, 2025). "However, it has been reported that JEV strain P20778 infection of Neuro2a cells activates autophagy through ERS-driven XBP1 and ATF6 pathways, thus inhibiting the replication of JEV." (PMID 39227990, 2024). "The ATF6 arm of the UPR pathway is not activated in the infection by the Asian and African strains, which suggests negative modulation during the infection." (PMID 39459886, 2024). "In addition, infection with the chikungunya virus (CHKV) can trigger activation of the IRE1 and ATF6 pathways while the PERK pathway is inhibited." (PMID 39227990, 2024). "In contrast, the expression levels of ATF6, cleaved-ATF6, and phosphorylation of IRE1 remained unchanged during infection, suggesting that neither the ATF6 nor the IRE1 branch was activated." (PMID 36939351, 2023). "Likewise, we observed the robust activity of ATF6α-controlled luciferase reporter gene over the course of VACV infections, which was distinguishable from mock-treated cells at late stages of infection." (PMID 37434252, 2023). "We observed a loss of GFP-ATF6-FL, as expected, and a concomitant and robust accumulation of a fragment of ATF6 fused to GFP at a MW of ∼60 kD (GFP-ATF6-LMW) 5 h post infection with WT L.p. but not ΔdotA L.p.." (PMID 34635501, 2021). "When cells were infected with ΔdotA L.p., ATF6-FL remained at pre-infection levels and treatment with MG-132 did not have a significant impact." (PMID 34635501, 2021). "Our results suggest that phospho-PERK but not phospho-eIF2α acts in synergy with the ATF6 pathway to facilitate ZIKV replication at an early phase of infection." (PMID 34106769, 2021). "Within 12 h of infection, Toxoplasma increased activation of PERK as measured by its self-phosphorylation (PERK-P), induced expression of ATF6 and formation of its cleavage product ATF6-N, and increased levels of the IRE1-derived spliced variant of XBP1 (XBP1s)." (PMID 32636244, 2020).
infection (continued). "In contrast, ATF6 was not activated, and the cleaved fragment of ATF6 was not detectable during infection." (PMID 31738790, 2019). "Notably, the transcription of CHOP, which usually increase in response to PERK- and ATF-6-mediated UPR responses, remained unaltered after infection with WT and ΔgD-2." (PMID 29176979, 2017). "Similarly, infection of Huh7.5 with JFH1 (2a) has been shown to transactivate the Bip, CHOP, and ATF6 promoters." (PMID 24904547, 2014). "The involvement of ATF6 pathway during infection of other coronaviruses has not been well characterized." (PMID 24987391, 2014). "The results shown in this study indicate that in a way similar to the other UPR sensors, ATF6 translocation to the nucleus is blocked at later times post infection, and instead colocalizes with VP6, again potentially affecting the efficiency of ATF6-dependent effector mechanisms." (PMID 21774819, 2011). "Surprisingly, SVCV does not modulate the ATF6 pathway under our infection conditions." (PMID 40248709, 2025). "Indeed, this was described for epithelial cells infected with HSV-1, in which only the ATF6 signaling pathway was activated early during infection, yet without the concomitant expression of target chaperones." (PMID 35069537, 2021). "However, ATF6 depletion did not affect viral yields indicating that the ATF6 pathway is dispensable during infection." (PMID 31467282, 2019). "ATF6 could have a cytoprotective role during milder infections such as WNVKUN, while remains nonessential for more pathogenic viruses such as DENV or TBEV." (PMID 31467282, 2019). "For instance, it has been documented that infection by the Hepacivirus hepatitis C virus (HCV) leads to the activation of the three UPR signaling pathways including BiP expression, IRE1 activation, and Xbp-1 splicing, ATF6 cleavage, eIF2α phosphorylation, and induction of CHOP expression." (PMID 24917859, 2014). "Infection of the hepatocyte sub-line Huh7.5.1 with JFH1 (2a) induced an acute ER stress peaking at 2–5 days post-infection (dpi), concomitant with phosphorylation of IRE1, eIF2α, and JNK, XBP1 splicing, ATF6 cleavage and upregulation of GADD34, ERdj4, P58IPK, ATF3, ATF4, and CHOP." (PMID 24904547, 2014). "For example, infection with WNV NY-99 strain activates all three pathways of the UPR, while infection with the WNVKUN strain activates the ATF6 and XBP-1 pathways but not the PERK pathway, and this may be due to differences in the viral strains and/or cell lines used." (PMID 30842332, 2019). "Conversely, the expression abundance of ATF6, cleaved ATF6, and p-IRE1 did not display fluctuation during infection, and the spliced form (XBP1s) of XBP1 was not detectable at the mRNA level." (PMID 36939351, 2023). "After infection for 4 h, the expressions of GRP78, EIF2α, P-EIF2α, and ATF4 were markedly increased, and those of ATF6 and P-IRE1α showed no significant changes." (PMID 35327108, 2022). "Both pathways were not activated in neuronal SH-SY5Y cells upon infection with TBEV Neudoerfl or LGTV, but were induced at 24 h in TBEV HB171 infected cells with ATF6 and p-eIF2α levels detectable even earlier than XBP1 in these cells." (PMID 34834970, 2021). "Infection of these cells with PRRSV revealed a reduction in virus titers when either ATF4 or XBP1s expression was reduced, but depletion of ATF6 did not have this effect." (PMID 31738790, 2019). "Taken together, the non-structural 2B protein of HRV16 induced an ER stress response, which was characterized by the induction of the ATF6 and PERK pathways rather than the IRE1 pathway during HRV16 infection." (PMID 30717233, 2019). "In our study, we confirmed that B.suis.S2 infection activated the IRE1 pathway and not the PERK and ATF6 pathways in GTCs." (PMID 26904517, 2016). "We concluded that infection with PRRSV induced ER stress, but not the ATF6 pathway." (PMID 32753633, 2020).
infection (continued). "The results reveal that activation of the ATF6 pathway was transient and occurred early in TMUV infection (from 12 h to 24 h post-infection), suggesting that ATF6 pathway activation may not play a major role in TMUV-induced UPR." (PMID 30670030, 2019). "By examining the three branches of UPR marker molecules PERK/eIF2α, ATF6, IRE1α/XBP1 splicing, we find that UPR did not occur until 24 h post-infection (hpi) as shown by elevation of phosphorylated form of PERK and eIF2α (p-PERK and p-eIF2α), a similar time point when autophagy was induced." (PMID 26907328, 2016).
neurodegenerative disease (10 papers, 2014 to 2023). A disorder of the central nervous system characterized by gradual and progressive loss of neural tissue and neurologic function. "Furthermore, ATF6 has been found to be closely associated with neurodegenerative diseases." (PMID 37376599, 2023). "WFS1 is a negative regulator of ER stress, a key event involved in the onset of neurodegenerative diseases, by preventing ATF6 activation thereby blocking the expression of proteins (CHOP, ATF4, BIP, and sXBP1) that promote cellular apoptosis." (PMID 36890518, 2023). "Other than the main effects of sleep deprivation on immune‐system function, plasma proteins associated with neurodegenerative diseases (APP, NOTCH3, SNCA, SOD1) were decreased after sleep deprivation, while only ATF6 continued to increase." (PMID 37139463, 2023). "Recent studies have demonstrated an involvement of the IRE1α-XBP1 and ATF6 pathways in human neurodegenerative diseases." (PMID 29725981, 2018). "The activation of the IRE1α-XBP1 and ATF6 pathways is triggered in ALS as well as other neurodegenerative diseases." (PMID 29725981, 2018). "GRP78 is a key regulator of ER stress transducer-ATF6α, and plays critical cytoprotective roles in neurodegenerative diseases." (PMID 25331812, 2014). "Furthermore, a small-molecule activator of ATF6 reduces amyloidogenic protein secretion and aggregation, providing additional justification for targeting the ATF6 pathway in neurodegenerative disease." (PMID 31852729, 2020). "ATF6 is also known to be activated in ALS and other neurodegenerative diseases." (PMID 31852729, 2020).
metabolic disease (6 papers, 2018 to 2025). A congenital disorder (due to inherited enzyme abnormality) or acquired (due to failure of a metabolically important organ) disorder resulting from an abnormal metabolic process. "The initiation-sensing proteins of ER stress, PERK, IRE1α, and ATF6 inhibitors can alleviate the activation of cell death and inflammatory pathways as well as metabolic disorders." (PMID 36232960, 2022). "Chronic ER stress, often seen in metabolic diseases, links oxidative misfolding to inflammation via protein kinase R-like endoplasmic reticulum kinase (PERK), activating transcription factor 6 (ATF6), and inositol-requiring enzyme 1α (IRE1α) signaling branches." (PMID 40563291, 2025).
cardiac disease (5 papers, 2018 to 2022). "In more recent studies a chemical biology approach has been taken in an effort to capitalize on the beneficial effects of ATF6 activation for the development of potential therapeutics for heart disease." (PMID 32322217, 2020). "ER stress effectors, particularly ATF6, are critical for the mitigation of myocardial tissue damage and the preservation of heart function during heart disease." (PMID 32085622, 2020). "Small molecule therapies to activate ATF6α in the context of cardiac disease are beginning to be explored in mice with evidence of improved contractile function after ischemia reperfusion injury, but this has yet to be extended to other larger animal models or other cardiac pathologies." (PMID 36425292, 2022). "For example, activation of the ATF6α branch of UPR is considered an adaptive responder to SR/ER stress and offers protective effects in many cardiac disease settings." (PMID 36425292, 2022). "The activation and differentiation of cardiac fibroblasts is a known feature of heart disease, however the role of ATF6 or the ER stress response in this process is not known." (PMID 32085622, 2020).